CCND1 (cyclin D1)
Diseases named in the same sentence as CCND1 in open-access papers (continued):
Sharing a sentence is not in itself a finding about the gene and the disease.
tumor (continued). "We thus determined the changes in expression of CCND1 between 82 paired tumor and normal tissues patient by patient." (PMID 32224897, 2020). "The oncogenic effect of cyclin D1 overexpression or gene amplification is primarily attributed to its impact on tumour cell proliferation, but proliferation‐independent oncogenic mechanisms have also been proposed." (PMID 32374893, 2020). "In contrast to cytoplasmic CCND1, nulcear CCND1 was found having a higher expression in tumor tissue (P < 0.001Figure 3(b))." (PMID 32566661, 2020). "Among selected hypoxia-related transcripts, we observed two significantly upregulated transcripts (Lox and Adm), and three significantly downregulated transcripts (Cdk20, E2f6, and Ccnd1) in tumor-bearing versus vehicle mice." (PMID 32151276, 2020). "Our study is a preliminary investigation mainly focused on the predictive function of CCND1 amplification in the tumor microenvironment in the aspect of genome and transcriptome." (PMID 32903763, 2020). "In the nucleus, EGFR plays a key role in transcription by acting as a transcriptional coactivator for genes, which initiate tumor formation such as cyclin D1." (PMID 33273921, 2020). "In this study, EHD not only slowed tumour growth in LC mice with PCBS syndrome but also regulated the STAT3/cyclin D1 signalling pathway." (PMID 32382281, 2020). "Nuclear PKM2 binds to STAT5a, facilitating the transcriptional activation of STAT5a target gene cyclin D1 and tumor growth." (PMID 33292198, 2020). "The previous PCa sequencing data of our institution explored that CCND1 expression level in adjacent normal tissues was higher than that in tumor tissues (P < 0.001Figure 1(e))." (PMID 32566661, 2020). "Western blotting analyses showed that protein expression of BRD4, c-Myc, Bcl-2 and cyclin D1, were significantly decreased in A1874-treated tumor tissues, where caspase-3 and PARP cleavage was detected." (PMID 32978368, 2020). "We also detected uniquely in C3N-02671 tumor tissue two protHLAIp TAAs (CCND1 and PXDNL) and five protHLAIIp TAAs (MMP2 and CEACAM5)." (PMID 32157095, 2020). "Studies have shown that expression of cyclin D1 and P21 is closely related to tumor occurrence, and that they are markers of proliferation of tumor cells." (PMID 32164618, 2020). "Several studies indicated that non-coding RNA was involved in tumor progression via regulating the expression of CCND1." (PMID 32003757, 2020). "Specifically, cytoplasmic-membranous Cyclin D1 expression correlates with the Gleason grade and, the higher expression is evidenced in pT3, that is, when tumor extends beyond the prostate." (PMID 33317149, 2020). "HIF1-α activates specifically pro-apoptotic genes, thus inhibiting tumor growth, while HIF2-α promotes tumor growth through the induction of pro-tumorigenic genes such as Cyclin D1 and VEGF." (PMID 32764403, 2020). "The Wnt/β-catenin pathway can affect tumor growth and metastasis by regulating the expression of downstream genes such as cyclin D1 and c-myc." (PMID 32908919, 2020). "The expression of GLUT1, MMP2, and cyclin D1 in the tumor tissues was also evaluated with western blot assays, and the results obtained were similar to the results in vitro." (PMID 32054829, 2020). "We have demonstrated that PPFIA1 mRNA was positively correlated with CCND1 mRNA levels in cases with luminal tumours." (PMID 32410585, 2020). "In non–small‐cell lung cancer, miR‐134 inhibited the expression of cyclin D1/2 and cyclin‐dependent kinase 4 by up‐regulating the expression of P21, thereby inhibiting the proliferation of tumour cells." (PMID 32916774, 2020). "Arsenic trioxide causes tumour cell differentiation, triggers cell apoptosis and induces G1 and/or G2-M phase arrest via down-regulation of CDK2, CDK6, cyclin D1, Cyclin E, Cyclin A and Cdc2 kinase." (PMID 32002123, 2020). "Analogously, the inhibitory effect of miR‐302e on tumor growth was effectively counteracted by restoration of circ‐CMPK1 or cyclin D1 expression." (PMID 31863641, 2020).
tumor (continued). "In fact, FH535 treatment reduced the expression of β-catenin, cyclin D1, c-myc and Ki67, impaired tumour growth and induced apoptosis." (PMID 33080952, 2020). "One of these miRNAs, miR-449b, is a tumour suppressor and inhibits CSCs proliferation by targeting cyclin D1 (CCND1) and E2F3 transcription factor." (PMID 32503256, 2020). "We first discuss the molecular basis underlying the role of Cyclin D1 in cancer initiation, progression and metastasis, and then, we highlight the role of Cyclin D1/CDK in the complex interplay between tumor and stroma." (PMID 33317149, 2020). "Other examples of tumor- specific cargoes are nuclear export of cyclin D1 mRNA in MCL, with decreased cyclin D1 levels upon inhibition of XPO1, and BCR-ABL in chronic myeloid leukemia (CML), as elaborated below." (PMID 32624581, 2020). "Like cytoplasmic LMW cyclin E, excessive cytoplasmic cyclin D1 also exerts oncogenic functions by promoting tumor cell invasion and metastasis through cytoplasmic interactions." (PMID 31884567, 2020). "SHP has also been shown to suppress tumor cell proliferation and invasion via transcriptional repression of cyclin D1 and Ccl2 expression." (PMID 32807788, 2020). "Molecular profiling analysis of the human tumor sample from which the PDX was derived revealed CCND1 amplification, suggesting its potential sensitivity to CDK4/6 inhibitors." (PMID 33116269, 2020). "Further, cyclin D1 and Pin1 expression levels have been shown to correlate positively in such cancers, thereby indicating Pin1 as a potential tumor-promoting factor." (PMID 31884567, 2020). "By preventing the tyrosine phosphorylation of STAT5, pimozide can decrease the expression of STAT5 target genes in KU812 and KU562 cells, such as Bcl-x, Pim-1, CIS, MCL-1 and cyclin D1, and reduce cell viability as well as induce apoptosis of the tumour cells." (PMID 32872372, 2020). "According to quantitative RT-PCR data in 30 LSCC patients, we observed that CCND1 was overexpressed in tumor tissues compared to normal tissues, which was further verified by immunohistochemistry analysis." (PMID 32380883, 2020). "For instance, EGFR inhibitor AG-490 can effectively suppress tumor cell proliferation by limiting the expression of cyclin D1." (PMID 33392203, 2020). "PLK1 inhibition results in tumour shrinkage in highly proliferating CCND1-driven PDX, including different RB-positive PDX with acquired palbociclib resistance." (PMID 32792481, 2020). "NF-κB promotes cells to pass the G1/S checkpoint by stimulating transcription of cyclin D1, which accelerates cell progression, promotes tumor growth, and leads to drug resistance." (PMID 32973135, 2020). "We show that PLK1 inhibition results in dramatic tumour shrinkage in highly proliferating CCND1-driven PDX including different RB-positive PDX with acquired palbociclib resistance." (PMID 32792481, 2020). "NPTX2, which was found to positively correlate with tumour stages, lymphatic invasion, distant metastasis, and poor patients’ outcome, promotes β-catenin nuclear translocation and the expression of c-myc, cyclin D1, Snail, and N-cadherin." (PMID 33080952, 2020). "Consistent with this cell cycle regulatory function, tumor cells overexpressing cyclin D1 display an uncontrolled proliferation." (PMID 32545704, 2020). "The analysis of TCGA samples further confirmed the high expression of E2F1 and CCND1 in tumor samples." (PMID 32796817, 2020).
tumor (continued). "We will also focus on recent insights regarding the Cyclin D1 as molecular bridge between cell cycle control, adhesion, invasion, and tumor/stroma/immune-system interplay in cancer." (PMID 33317149, 2020). "Differential methylation analysis identified CCND1, encoding cyclin D1, as a plausible cancer driver gene in these tumours because hypermethylation of the CCND1 promoter was specific for GCTBs." (PMID 32866294, 2020). "Results of in vivo xenograft tumour model of DU145 cells also revealed that up‐regulation of Cyclin D1 expression rescued the growth inhibition of tumour after HNF1B overexpression." (PMID 33174391, 2020). "Highly expressed YTHDF2 promotes tumor proliferation by activating the AKT/GSK3 β/cyclin D1 pathway and suppresses migration and invasion by binding m6A sites on and decomposing yes-associated protein (YAP) mRNA." (PMID 33062408, 2020). "CRISPR/Cas9-mediated knockout of SHP2 decreased Cyclin D1 protein abundance and consequently resulted in cell cycle defects and diminished cell proliferation in vitro and tumor growth in vivo." (PMID 32944401, 2020). "We considered CCND1 to be deregulated in the tumor if the fold-change of expression between tumor and normal tissues was above two (CCND1 upregulation) or less than 0.5 (CCND1 downregulation), respectively." (PMID 32224897, 2020). "Among 12 candidate target genes, E2F1 and CCND1 were significantly downregulated by miR-93, and they were overexpressed in tumor tissues compared with matched adjacent normal tissues of clinical specimens." (PMID 32796817, 2020). "In tumor cells, due to the difference in a cellular context and signaling pathway, the cyclin D1 expression is often mediated by different transcription factors." (PMID 32566659, 2020). "Reduced COX-2 protein expression has also been observed in a murine model with orthotopic MB49 tumor cell implants, with Cyclin D1 decreasing concomitantly." (PMID 32466578, 2020). "The main model (model 1), including fibronectin and cyclin D1 combined with preoperatively available tumour grade, is to our knowledge the first protein-driven model to predict LNM in EEC." (PMID 32037399, 2020). "If CCND1 amplification was present in the primary tumours, CDKN2A homozygous deletion appeared in the bone metastases (HBCx-131) or in the PDX (HBCx-134), in patients who recurred 10 years and 1 year, respectively, after treatment with an aromatase inhibitor." (PMID 32792481, 2020). "In this study, we found that both hBMSCs and hFOB1.19 cells enhanced cyclin D1 expression in PC3 cells, and their effects on the proliferation of PC3 cells are consistent with a role for cyclin D1 as an enhancer of tumor cell growth." (PMID 32337233, 2020). "The overexpression of cyclin D1 and p21 is reported in human cancers and correlated with a high tumor grade and poor prognosis." (PMID 32405344, 2020). "In tumor cells, CCND1 can accelerate tumor cell division from the G1 phase to the S phase, thereby improving the proliferation ability of tumor cells; c-Myc is a nuclear protein gene with multiple cell biological functions." (PMID 33304892, 2020). "BRD4 protein degradation as well as c-Myc, Bcl-xL and cyclin D1 downregulation were detected in ARV-825-treated TPC-1 tumor tissues." (PMID 32163373, 2020). "The overexpression of cyclin D1 plays an important role in tumor progression of Colon Rectal Cancer (CRC) and it represents an unfavorable CRC prognostic factor." (PMID 33339392, 2020). "In our study, although the CCND1 mRNA level and cytoplasmic CCND1 were both found higher in adjacent normal tissue, nuclear CCND1 was found higher in tumor tissue." (PMID 32566661, 2020). "Some authors suggested the capacity of neratinib to block CCND1 (cyclin D1) and through this mechanism to maintain tumor suppression." (PMID 32210163, 2020).
tumor (continued). "IHC assays also demonstrated that upregulation of circCCDC9 enhanced the expression of CAV1, E-cadherin and weakened the expression of β-catenin, cyclin D1 and Ki-67 in xenograft tumor tissues." (PMID 32386516, 2020). "CCL5 increases tumor growth by activating STAT5 and cyclin D1 pathways, enhanced tumor invasion and synergizes with IL-6." (PMID 32630699, 2020). "By contrast, it has been reported that 4EBP1 is also involved in promoting tumor progression by enhancing the translation of a selected subset of mRNA, such as c-Myc, Cyclin D1, HIF1, and VEGF, especially under stress conditions." (PMID 32075852, 2020). "In the group of 15 predominantly HPV(−) cases where CCND1 expression was upregulated in the tumor tissues (FC > 2), we observed upregulation of the genes that were downstream of CCND1 in 14 (93%) cases." (PMID 32224897, 2020). "Both doses of 6-gingerol attenuated immunohistochemical staining of p-AKT Ser 473 and cyclin D1 in the tumor tissues, whereas strong staining of GSK 3β was observed in high dose of 6-gingerol treatment group." (PMID 31832810, 2020). "The polyphenols of tea suppress the migration of proliferation abilities of tumor cells by inhibiting NF-κB activation and quenching the expression of cyclin D1." (PMID 32085594, 2020). "We also measured AKT, p-AKT Ser 473, GSK 3β, p-GSK 3β Ser 9, CDK4, and cyclin D1 in tumor tissue by western blotting." (PMID 31832810, 2020). "Palbociclib was initially tested in both in vitro and in vivo models of breast cancer and was shown to effectively inhibit the growth of tumor cells, especially cell lines with increased RB phosphorylation and cyclin D1 expression and decreased p16 expression." (PMID 33243298, 2020). "Cyclin D1 is involved in tumor cell proliferation, survival of the metastatic seed, tumor expansion and drug resistance." (PMID 32872485, 2020). "In normal cells, CDK4/6 is rigorously regulated by members of the INK4 CDK inhibitor family; however, genetic changes or overexpression of cyclin D1-3, CDK4/6, and INK4 family members cause the cell cycle to become dysregulated, resulting in tumor formation." (PMID 33271970, 2020). "In tumor cells, overexpression of cyclin D1 and down-regulation or dysfunction of its negative regulatory proteins P21 and P27 are very common, these changes are closely related to the abnormal proliferation of tumors." (PMID 31840737, 2020). "We also found LOH at the CDKN2A gene locus and abundant Cyclin D1 expression in the tumor in this VHL patient." (PMID 31673890, 2020). "Since Cyclin D1 increases the mobility and invasion of tumor cells, the overexpression of Cyclin D1 is related to the aggressiveness of PC." (PMID 32552908, 2020). "Xenograft tumor model was established to evaluate the role of circ‐CMPK1/miR‐302e/cyclin D1 axis in vivo." (PMID 31863641, 2020). "Further analysis showed that most CNAs, including amplification in AR and deletion in PTEN in P8, amplifications in ELF2 and MYC in P9, and amplifications in MYC and CCND1 in P11, were concordant in the plasma and tumor tissues." (PMID 32631448, 2020). "By immunohistochemistry, tumor cells demonstrated strong nuclear cyclin D1 expression and multifocal smooth muscle actin staining but were negative for MUC4, ERG, CD34, S-100 protein, desmin, STAT6, CD45, MDM2, CDK4, ALK, and ROS1." (PMID 32461620, 2020). "Tumor proliferation-associated proteins of PCNA and Cyclin D1 were detected by Western blot assay, whereas cell proliferation was detected by CCK-8 assay." (PMID 33553160, 2020). "In CRC tumor tissues we found 55.2% nuclear positivity for cyclin D1 protein, whereas in GC it positivity is lower (28.6%)." (PMID 32102509, 2020). "The high expression of Cyclin D1 drives unchecked cellular proliferation promoting tumor growth, thus, the Cyclin D1 carries out a central role in the pathogenesis of cancer." (PMID 33317149, 2020).
tumor (continued). "Cyclin D1 (CCND1) controls the transition of the cell cycle, principally regulating the G1-S phase, and playing an important role in the transcription of tumor genes and cell proliferation." (PMID 33042832, 2020). "In mice, fruti prevented tumor development and reduced Cyclin D1, Bcl-2 and Rela gene levels, and reduced the p-NF-κB/NF-κB ratio in tumor tissue." (PMID 33020521, 2020). "The Wnt/β-catenin target genes Axin2, c-myc and Ccnd1 were also significantly decreased in WlsΔOB-OS tumor-bearing bones and primary OS cells, while endogenous c-fos and the c-fos transgene were not affected." (PMID 32686768, 2020). "CSO significantly down-regulated S1PR1 and Cyclin D1 expression and upregulated the expression level of p27 in tumor tissues and cells." (PMID 33101013, 2020). "As expected, the volume and weight of subcutaneous tumours in the circ‐CCND1‐depleted group were less than those in the control group (n = 8 in each group)." (PMID 31951319, 2020). "Target 2, which resided 1.06 mm from target 1, exhibited tumor cells containing both strongly amplified MET and CCND1, 3 to 4 copies of EGFR, 3 to 4 copies of FGFR2, and loss of both copies of the genes encoding PD-L1/PD-L2." (PMID 32338752, 2020). "Cyclin D1 has also other functions: it governs the expression of specific miRNAs and it plays a crucial role in the tumor-stroma interactions potentiating most of the cancer hallmarks." (PMID 33317149, 2020). "As well, due to the predictive preoperative usefulness of the Gleason score correlated with Cyclin D1 expression to predict tumor behavior, it became easy to differentiate between malignant and benign disease." (PMID 32552908, 2020). "NF‐κB–associated proteins involved in tumour progression, such as MMP‐2, MMP‐9, uPA, VEGF, XIAP and Cyclin D1, were all decreased by imipramine." (PMID 32149465, 2020). "Further supporting this notion, we found that the expression of Cyclin D1 was more significantly upregulated in the tumor of Atg7ΔHep liver than in the tumors of the Atg7/Hmgb1ΔHep livers." (PMID 32382012, 2020). "The cytoplasmic CCND1 also showed correlation with several clinical factors, e.g., tumor T stage (P < 0.001), Gleason score (P = 0.028), positive surgical margin (P = 0.037), and capsule invasion (P = 0.04)." (PMID 32566661, 2020). "TRIM33 overexpression reduced the expression levels of β-catenin, cyclin D1, and c-myc, and inhibited tumor growth in ccRCC cells in vivo." (PMID 32908919, 2020). "LPP1 expression also inhibited tumor growth and metastasis, which we related to the decreased production of MMPs and cyclin D1/D3." (PMID 31534541, 2019). "Previous reports stated that the upregulation of Chk1, Chk2, and cyclin D1 promotes tumor cell growth." (PMID 32010609, 2019). "In this report, we demonstrated that emetine suppresses tumor cell proliferation by inhibiting Wnt//β-catenin signaling and its target genes, such as c-myc and cyclin D1." (PMID 31775307, 2019). "Data obtained from murine cancer models supports a mechanistic role for RAGE activation whereby induction of cell signaling proteins such as AKT proteins, the anti-apoptotic protein, BCL2, and cyclin D1, promote tumor cell proliferation." (PMID 31665084, 2019). "According to the ROC analysis, the area under the curve (AUC) of the nomograms for recrudescent probability based on tumor grade and CCND1 was 0.637 and 0.674, respectively." (PMID 31183974, 2019). "There was a striking decrease of Cyclin D1 and Cyclin E1 protein expression in the NanoTLZ treated tumor lysates, indicating cell cycle arrest." (PMID 31534547, 2019). "Decreased expression levels of the proliferation-related genes PCNA and cyclin D1 were observed in the tumor tissues of Ct55 knockout mice by qRT-PCR." (PMID 30944312, 2019).